INS (insulin)
Diseases named in the same sentence as INS in open-access papers (continued):
Sharing a sentence is not in itself a finding about the gene and the disease.
Obesity (continued). "Studies have demonstrated that Bifidobacterium can improve fasting serum insulin, restore colonic mucus growth, reduce hepatic triacylglycerol accumulation, and alleviate obesity development by increasing acetate levels in HFD mice." (PMID 35807856, 2022). "On the other hand, overexpression of UCP2 proteins in mice decreases obesity and improves insulin sensitivity." (PMID 35323702, 2022). "IR, defined as the reduced ability of insulin to control the breakdown of glucose in target organs, represents the common thread among obesity, metabolic syndrome and type 2 diabetes mellitus." (PMID 35282448, 2022). "MCP1 increases lipolysis and leptin secretion while lowering insulin-stimulated glucose uptake, increasing plasma levels during obesity, contributing to impaired insulin sensitivity." (PMID 35422689, 2022). "Persistent overweight and obesity alters metabolic processes, including the hypoglycaemic action of insulin, lipid metabolism and blood pressure, leading to a condition known as metabolic syndrome (MetS)." (PMID 35883817, 2022). "Adipocyte irregularities with consequential chronic low-grade inflammation and reduced insulin sensitivity are quite common in the pathogenesis of obesity-related metabolic disorders." (PMID 35700181, 2022). "Obesity is related with decreased insulin-stimulated glucose uptake and metabolism in the skeletal muscle and adipocytes." (PMID 35745174, 2022). "Previous data showed that Kv1.3 mice exhibit increased insulin sensitivity, reduced plasma glucose concentrations and resistance to diet-induced obesity, weighing significantly less than controls, despite the same amount of food ingested." (PMID 36501016, 2022). "Future investigations should examine how the neural responses to food cues in lean individuals and individuals with obesity are altered by IN insulin depending on their fed versus fasted state." (PMID 35397638, 2022). "Sortilin is involved in many facets of cardiovascular and metabolic disease pathogenesis, including atherosclerosis, lipoprotein metabolism, vascular calcification, obesity, insulin resistance, and glucose homeostasis." (PMID 35724703, 2022). "The anti-obesity potential effects of CK were investigated in obese mice, including through whole-body energy homeostasis, glucose and insulin tolerance, and biochemical and proteomic analysis." (PMID 35745765, 2022). "A common characteristic of obesity is high circulating lipid levels, partly accounted by impaired insulin‐mediated suppression of lipolysis." (PMID 36062491, 2022). "The core acupoint combinations found in our article can improve simple obesity by increasing the levels of serum insulin and C peptide and by remodeling WAT to brown adipose tissue (BAT), which has been supported by many modern pharmacological studies." (PMID 35341146, 2022). "Daily consumption of almonds increased the intake of MUFA with decrease in carbohydrate calories and decreases insulin resistance, improves insulin sensitivity and lowers serum cholesterol in Asian Indians with overweight/obesity." (PMID 36704786, 2022). "Other factors capable of influencing insulin sensitivity include obesity, ethnicity, sex, perinatal factors, puberty, sedentary lifestyle, and diet." (PMID 36364954, 2022). "The subgroup analysis according to country or overweight and obesity indicated that these associations remained significant between FMP and INS or HOMA-IR." (PMID 35684072, 2022). "These four months of follow-up showed a significant improvement in PCOS-related symptoms, especially a decrease in hirsutism, obesity, and insulin and serum concentrations of testosterone." (PMID 35924049, 2022). "Expectedly, a reported 2- to 3-fold increase in insulin secretion is observed in individuals with obesity and prediabetes due to β-cell compensation, which is shown to eventually lead to β-cell damage and reduction in β-cell mass/volume." (PMID 36584200, 2022).
Obesity (continued). "Obesity in children and young adults with T1DM results in worse metabolic control, insulin resistance, and increased risk for vascular complications." (PMID 36578961, 2022). "Many factors like obesity, an increase in the inflammatory markers in the insulin target tissue, and an increase in IR and amount are associated with developing T2DM." (PMID 36168335, 2022). "Insulin-resistant states such as dietary obesity in mice and humans are associated with reduced adipose and/or serum PAHSA levels, and PAHSA administration to insulin-resistant mice enhances insulin sensitivity." (PMID 35676490, 2022). "Activated by diabetogenic stimuli in several experimental models of obesity-associated T2D and immune-mediated T1D in vitro and in vivo, MST1 directly triggers β-cell apoptosis and impairs insulin secretion." (PMID 35136036, 2022). "Although the pathophysiology of hyper-androgenemia in peri-pubertal girls with obesity is yet unclear, insulin resistance with compensatory hyperinsulinemia probably plays a key role." (PMID 35412268, 2022). "Most studies in animals and humans have shown that hepatic insulin clearance is defective in obesity and insulin resistance states." (PMID 36009446, 2022). "Our study shows that increasing liver ARSA expression and secretion via adeno-associated virus delivery was sufficient to improve whole-body glycemic control in obesity, which was mediated by improvements in skeletal muscle insulin action." (PMID 35273160, 2022). "As an anti-inflammatory cytokine, IL-10 has been suggested to attenuate AT inflammation and improve insulin sensitivity in conditions of obesity." (PMID 35909571, 2022). "The population of this last study had twice as many patients with obesity and about half of patients using insulin compared to our study." (PMID 35657127, 2022). "Recently, our report revealed the clinical insulin sensitizer metformin modulates PDIA4 and adiponectin expression and improves obesity-associated conditions in both in vitro adipocytes and in vivo mouse models." (PMID 36619574, 2022). "Similarly, GDF15 transgenic mice fed a HFD show reduced NLRP3 inflammasome activity and pro-inflammatory macrophage infiltration into white AT as well as lower serum leptin and insulin levels, suggesting that GFD15 could reduce obesity-associated inflammation and improve insulin sensitivity." (PMID 35909571, 2022). "Thirdly, diet enriched with nuts may improve insulin sensitivity and fasting glucose levels, therefore, nut consumption could contribute to better metabolic status, decreased body weight as well as lower body weight gain over time and thus reduce the risk of obesity." (PMID 36570151, 2022). "Most women with PCOS are metabolically resistant to insulin, either owing to genetic propensity or obesity." (PMID 36407241, 2022). "Ectopic ceramide accumulation in insulin-responsive tissues contributes to the development of obesity and impairs insulin sensitivity." (PMID 35508667, 2022). "Investigators showed an arginine-rich diet, known to reduce obesity and increase insulin sensitivity, corrects the elevated F/B ratio, and increases embryo survival." (PMID 35413875, 2022). "If the Carbohydrate-Insulin model best reflects the etiology of obesity, individuals with obesity should have increased glucose variability with higher amplitude glucose spikes and lower nadirs." (PMID 36570168, 2022). "For instance, genetic approaches have revealed pleiotropic actions of ROCKs in regulating insulin signaling and obesity, and the ultimate phenotype depends on ROCK isoforms and metabolic organs." (PMID 35769086, 2022). "This was consistent with studies suggesting that dyslipidemia through obesity is related to weight distribution, insulin sensitivity, and impaired glucose tolerance." (PMID 35889886, 2022).
Obesity (continued). "Increases in estrogen and insulin seen in women with obesity lead to an activation of downstream PI3Kinase and MAPKinase pathways through a phosphorylation of AKT and ERK leading to increased cell proliferation and inhibited apoptosis." (PMID 36117808, 2022). "Healthy animals fed a high-fat diet (HFD), even with moderately raised fat content (1.8-fold) or for a short duration (3 days), have reduced MBF responses to the insulin that occurs before the development of obesity or myocyte/whole-body insulin resistance." (PMID 35676248, 2022). "Previous studies have demonstrated that A. muciniphila can ameliorate obesity, insulin sensitivity, and endotoxinemia." (PMID 36246928, 2022). "GIP has been shown to increase AT blood flow in the presence of insulin, the response being blunted in obesity, possibly due to insulin resistance." (PMID 35363252, 2022). "As previously reported, IL-15 is a regulator of obesity related pathological changes, and can modulate insulin sensitivity." (PMID 35250857, 2022). "Mfn2 deletion in these neurons prevents these adverse metabolic effects: fat mass was reduced, insulin and glucose levels were legitimized, and obesity was avoided." (PMID 35898328, 2022). "We also point out that the Sort1–/– mouse model used in these experiments was protected from diet-induced obesity, was more insulin sensitive, and had decreased hepatic steatosis, as shown in a report from an another group." (PMID 35113816, 2022). "The results showed that obesity influenced metabolic variables (including fast/fed glucose, insulin, and triglyceride), retinopathy and nephropathy, and the gut microbiota." (PMID 36406423, 2022). "The analysis of obesity-associated serum parameters showed that CAF feeding increased glucose, triacylglycerides, insulin, HOMA-IR, leptin, adiponectin, and the leptin/adiponectin ratio compared to STD feeding." (PMID 36379981, 2022). "The researchers concluded that a lengthened duration of obesity can lead to muscle strength decline by means of inflammation and insulin resistance, which have catabolic effects on muscles." (PMID 36585620, 2022). "Exenatide has a better hepatic-protective effect than intensive insulin therapy and, perhaps, represents a unique option for adjunctive therapy for patients with obesity, NAFLD with elevated liver enzymes and T2DM." (PMID 35268466, 2022). "For example, some studies suggest that a bile acid (BA)-gut microbiome axis contributes to insulin sensitivity and obesity." (PMID 35873174, 2022). "The expression of NAMPT and the level of NAD+ are reduced in WAT during obesity, and NAMPT deficiency in adipocytes markedly alters the endocrine function of WAT and the insulin sensitivity." (PMID 36010657, 2022). "Evidence on the subject has found that in POMC neurons, overexpression of the unfolded protein response transcription factor (Xbp1s) decreases the expression of PTP1B and SOCS3, improves leptin and insulin sensitivity, and protects against obesity." (PMID 35563589, 2022). "Mice fed with an HF diet and on CA supplementation showed decreased bodyweight, glucose levels, and insulin levels compared with control mice, indicating that CA has anti-obesity properties." (PMID 35408495, 2022). "In overweight/obesity conditions, when β-cells are exposed to chronically excess nutrients, insulin secretion initially increases, but eventually β-cell dysfunction and death occur." (PMID 35457000, 2022). "Studies in models of obesity reflect that SIRT3 can act as a positive regulator of insulin sensitivity in human and mice endothelial cells." (PMID 35369299, 2022). "Obesity and fat accumulation in the liver and extrahepatic tissues are considered important determinants of IR, which explain the need for higher doses of insulin and worse glycemic control." (PMID 35657127, 2022).
Obesity (continued). "The resulting improvements in glucose homeostasis and insulin sensitivity resulting from these effects have identified the GCGR as a target for the treatment of obesity, type 1, and type 2 diabetes." (PMID 36009454, 2022). "Transgenic orexin overexpression counteracted obesity induced by the high-fat diet and insulin insensitivity by promoting energy expenditure and reducing exertion." (PMID 36397166, 2022). "In obesity, the endocannabinoid system is often highly active, while its ablation or inhibition reduces body weight and improves insulin sensitivity." (PMID 35789435, 2022). "Obesity-related increase in FFA concentrations induces insulin resistance by increasing ROS products." (PMID 36235772, 2022). "GDM was associated with subclinical inflammation, and affected women showed increased plasma leptin and lower plasma adiponectin levels independently of the degree of insulin sensitivity or obesity." (PMID 36432399, 2022). "On the contrary, glucose and insulin levels were the highest in the subgroup with obesity and the lowest in the normal weight subgroup." (PMID 35140785, 2022). "The notoginsenosides found in DKP are potential active ingredients for the treatment of obesity by reducing lipid synthesis, inhibiting adipogenesis, increasing energy expenditure, and improving insulin sensitivity." (PMID 36062168, 2022). "In summary, our findings help explain the influences of genetic background and dietary macronutrient composition on clinically significant genes involved in insulin response relative to obesity development." (PMID 35945490, 2022). "Compared with general obesity and subcutaneous fat, visceral fat accumulation had a significant negative effect on blood glucose control by reducing peripheral insulin sensitivity and enhancing gluconeogenesis, which was closely related to IR." (PMID 35432185, 2022). "Obesity is also related to lower adiponectin levels, which have anti-tumor effects by increasing insulin sensitization and eliminating growth factors required for the development of tumor cells." (PMID 35892729, 2022). "The number of patients on intensive therapy and using insulin analogs increased significantly from 1986 to 2007 as did the rate of overweight and obesity, coinciding with the obesity pandemic." (PMID 35549683, 2022). "It is involved both in the recruitment of monocytes and T lymphocytes, thus triggering the beneficial inflammation essential to support muscle regeneration but also in the alteration of insulin sensitivity and obesity-related low-grade inflammation." (PMID 35631195, 2022). "Among the many proposed roles of GSK-3 signaling, the most established are its critical regulatory functions in glucose metabolism, insulin activity, and obesity." (PMID 35159367, 2022). "In severe obesity, impaired insulin-stimulated glucose uptake, oxidative metabolism, and increased lactate production have been observed in skeletal muscle." (PMID 36552805, 2022). "A second model for obesity, the Carbohydrate-Insulin model, posits that a high-carbohydrate diet drives post-prandial hyperinsulinemia, leading to increased fat storage." (PMID 36570168, 2022). "Adiponectin is released from adipose tissue, increases insulin sensitivity, and is present at low levels in people with obesity." (PMID 35629208, 2022). "In the central nervous system, the CBS/H2S pathway in the paraventricular nucleus improved obesity and insulin sensitivity by regulating the neuroendocrine hormones via the brain–adipose interaction in the HFD rats." (PMID 35681432, 2022). "Our study shows a complex interaction between sex and obesity during neural FCR, which is associated with peripheral insulin sensitivity and cognitive restraint, which indicates that further factors likely contribute." (PMID 35715625, 2022).
Obesity (continued). "High-fat diet (HFD) consumption is known to trigger an inflammatory response in the brain that prompts the dysregulation of energy balance, leads to insulin and leptin resistance, and ultimately obesity." (PMID 36507349, 2022). "Improved whole-body energy metabolism, increased insulin sensitivity, and reversed preexisting obesity." (PMID 36714578, 2022). "The molecular mechanisms of the relationship between obesity and breast cancer involve estrogens, insulin, leptin, adiponectin, and inflammatory cytokines." (PMID 35223490, 2022). "The present study found that fasting blood glucose and insulin levels at 14 weeks were significantly higher in WT mice with HFD-induced obesity than in SFD-fed WT mice." (PMID 35807921, 2022). "Several clinical trials have been reporting the positive effects of this approach on several indicators of glucose metabolism, including HOMA-IR, insulin levels, adiponectin, and resistin, in children and adolescents with obesity." (PMID 36364954, 2022). "Honey supplementation prevented the down/upregulation of these alterations associated with HFD consumption, suggesting that chronic honey ingestion improves the impairment of insulin signaling in obesity conditions." (PMID 35215406, 2022). "Preclinical models of obesity that chronically consumed different bioactive compounds showed improvement in serum lipids (TG, HDL-cholesterol, and LDL-cholesterol) and insulin sensitivity associated with weight." (PMID 36778595, 2022). "Many people with obesity show elevated levels of plasma free fatty acids (FFAs), which is partly attributable to unopposed lipolysis in adipocytes secondary to decreased insulin sensitivity and impaired adipose tissue function." (PMID 35789435, 2022). "Another demonstrated that moderately elevated testosterone concentrations, together with obesity-related inflammatory factors, modify glucose homeostasis by increasing insulin resistance and early insulin secretion." (PMID 35842601, 2022). "This is likely exacerbated by obesity precipitated changes in β-cell insulin secretion and intestinal ApoC-ii expression, namely a basal elevation with a loss of nutrient stimulation in both." (PMID 36111295, 2022). "It is known that jetlag induces obesity and increases weight; we found that metabolic functions and insulin-related pathways were affected in the mice treated with CJL." (PMID 36582489, 2022). "This allows us to suggest that in insulin-sensitive obesity conditions, Ang II levels are lower than in the resistance condition." (PMID 35682723, 2022). "Special attention will be paid to their signaling pathways and targets related to body weight, feeding, glucose and insulin homeostasis as well as to adiposity, inflammation, oxidative stress and vascular dysfunction in obesity." (PMID 35458168, 2022). "Our mediation analyses showed that obesity had an indirect effect on intermediate hyperglycemia and that insulin mediates this relationship." (PMID 35757631, 2022). "Excessive fat storage in obesity leads to adipose tissue dysfunction, lipotoxicity, inflammation, ectopic lipid deposition, and insulin resistance." (PMID 35683979, 2022). "In the obesity subgroup, there was an increased proportion of individuals with higher BMI, HC, and fasting insulin and ACTH levels in the highest TSH quartile group (p=0.004 for BMI, p=0.045 for HC, p=0.045 for fasting insulin level, p < 0.001 for ACTH level)." (PMID 35311031, 2022). "Obesity and glucose/insulin-related characteristics that are genetically determined significantly influence the etiology of BC." (PMID 35145826, 2022). "Based on the scientific evidence, most of the studies found that higher serum phosphate level prevented obesity, improved postprandial blood glucose level, lowered insulin resistance, and increased insulin sensitivity." (PMID 36364791, 2022).